CREB1 (cAMP responsive element binding protein 1)
Diseases named in the same sentence as CREB1 in open-access papers (continued):
Sharing a sentence is not in itself a finding about the gene and the disease.
gastric cancer (58 papers, 2009 to 2026). A primary or metastatic malignant neoplasm involving the stomach. "In the present study, we demonstrate, for the first time, that CREB1 is overexpressed in gastric cancer and associated with poor outcome in patients with gastric cancer." (PMID 25825983, 2015). "As CREB1 expression was significantly overexpressed and correlated with aggressive clinical characteristics in gastric cancer, we further evaluated the association of CREB1 expression with the prognosis of gastric cancer patients." (PMID 25825983, 2015). "High expression of CREB1 was associated with poor outcome in gastric cancer patients." (PMID 25825983, 2015). "However, the expression and clinicopathological significance of CREB1 in gastric cancer, especially the underlying mechanisms of CREB1 expression are still not well understood." (PMID 25825983, 2015). "CREB1 is classified as a potential biomarker for tumor metastasis and patient outcome in gastric cancer." (PMID 40227324, 2025). "In conclusion, lncRNA PIN1P1 has been identified as an effector of gastric cancer progression and is transcriptionally induced by CREB1." (PMID 37929660, 2024). "Analyses using TCGA database showed that CREB1 levels were significantly higher in gastric cancer tissues than in normal mucosae (P < 0.001), which was confirmed by IHC assays with human stomach tumour tissues." (PMID 38862740, 2024). "Here, we investigated a novel lncRNA, PIN1P1, upregulated in gastric cancer and transcriptionally activated by CREB1." (PMID 37929660, 2024). "We have shown CREB1 is overexpressed in gastric cancer and predicts metastasis, advanced stage and poor prognosis." (PMID 37929660, 2024). "Here, we show that lncRNA PIN1P1 is one of the direct target genes of CREB1 in gastric cancer and is transcriptionally activated by CREB1." (PMID 37929660, 2024). "And through rescue experiments, we found that PIN1P1 is a functional target of CREB1 in promoting the tumorigenesis of gastric cancer." (PMID 37929660, 2024). "Bioinformatics analyses also showed a positive correlation between SRGN and CREB1 in gastric cancer (P < 0.001)." (PMID 38862740, 2024). "We have previously performed a genome‐wide screening of CREB1 targets by ChIP‐seq in gastric cancer cells (GEO database GSE220708) and found numerous targets of CREB1, in which PIN1P1 was involved." (PMID 37929660, 2024). "GATA6 which located on chr18q11.2 locus (amplified in ITGB1 low subgroup), suppressed migration and metastasis by regulating the miR-520b/CREB1 axis in gastric cancer." (PMID 37007126, 2023). "Eventually, TCEAL2 and MBNL1 were proved to be differentially regulated by CREB1 during tumorigenesis of gastric cancer." (PMID 35421923, 2022). "Based on dataset GSE54129, involving 111 gastric cancer and 21 normal mucosa samples, we identified four TFs including CREB1, BPTF, GATA6 and CEBPA with high DR value among top 1% DRGs." (PMID 35421923, 2022). "UCA1 down-regulates gene CREB1 expression by sponging microRNA miRNA-590-3p, promoting cells proliferation and invasion of gastric cancer, thus acting as an oncogene." (PMID 35402492, 2022). "In conclusion, this study uncovered miR-585-5p impedes gastric cancer proliferation and metastasis by orchestrating the interactions among CREB1, MAPK1 and MITF." (PMID 36268034, 2022). "Collectively, miR-450a-5p repressed gastric cancer cell proliferation, migration and invasion and induced apoptosis through targeting CREB1 by inhibiting AKT/GSK-3β signaling pathway." (PMID 33854971, 2021). "For example, GATA6 suppresses gastric cancer cell migration and metastasis via the miR-520b-mediated repression of CREB1." (PMID 33659248, 2021). "IGF2-AS has been reported to play anti-cancer efficacy via ceRNA mechanism in some other cancers, such as in gastric cancer via miR-195/CREB1 axis and in gastric adenocarcinoma via miR-503/SHOX2 axis." (PMID 34516353, 2021).
gastric cancer (continued). "CREB1 was highly expressed in tumor cells, such as human gastric cell lines and knockdown of CREB1 inhibited human gastric cancer cells growth." (PMID 32699307, 2020). "In contrast, CREB1 immunoreactivity was predominantly identified as positive in the majority of primary gastric cancer tissues." (PMID 25825983, 2015). "The gastric cancer cells were co-transfected with miR-27b (15 nM) and miR-200b (15 nM), and subjected to luciferase assay and CREB1 expression detection." (PMID 25825983, 2015). "In the present study, immunohistochemistry was performed to detect the expression of CREB1 protein in 185 primary gastric cancer tissues, 50 secondary lymph node metastatic foci and 50 nontumorous gastric tissues." (PMID 25825983, 2015). "All these data suggested an interesting link between CREB1 and gastric cancer metastasis and progression." (PMID 25825983, 2015). "Collectively, our data demonstrated that CREB1 was highly expressed and correlated with metastasis, tumor stage in gastric cancer." (PMID 25825983, 2015). "It was shown that CREB1 was highly expressed and correlated with lymph node metastasis, distant metastasis and tumor stage and poor outcome in gastric cancer." (PMID 25825983, 2015). "To further assess the clinical significance of CREB1 in gastric cancer, we analyzed the correlation between CREB1 expression and clinicopathological factors in primary gastric cancer." (PMID 25825983, 2015). "The current study reports, for the first time, that high expression of CREB1 was indicative of poor prognosis in gastric cancer." (PMID 25825983, 2015). "In contrast, this miRNA inhibits cell proliferation and colony formation and induces apoptosis in gastric cancer by targeting CREB1 and reduces drug resistance in pancreatic cancer by inhibiting CYLD and BCL-2." (PMID 25299073, 2014). "Furthermore, tumour-associated neutrophils (TANs)-derived regenerating family member 4 (REG4) upregulates SRGN expression by activating cAMP-responsive element binding protein 1 (CREB1) in gastric cancer cells." (PMID 38862740, 2024). "Furthermore, the expression of CREB1 in gastric cancer tissues was positively related to PIN1P1 expression (Spearman r = 0.5168, p < 0.0001)." (PMID 37929660, 2024). "Through mutual verification of computational analysis, clinical pathology and biological experiments, we have obtained reliable and consistent results to support our hypothesis on the dysfunctional mechanism of CREB1 during gastric cancer progression." (PMID 35421923, 2022). "Additionally, silencing of IGF2-AS downregulates CREB1 expression through sponging miR-195 to retard tumorigenesis of gastric cancer." (PMID 35693981, 2022). "CREB1 has been reported to be related with metastasis, tumor stage and poor outcome in gastric cancer, and the knockdown of CREB1 could inhibit liver cancer cell migration." (PMID 34796177, 2021). "In addition, CREB1 has also been reported to be directly related to the ability of colon, breast, and gastric cancer to metastasize." (PMID 33921660, 2021). "Among the top 10 DRGs for Chinese (GSE54129), six genes have been reported to be gastric cancer (GC) related (REG4, ANXA13, C7, ASS1, MSMB, CREB1) and the rest four were directly regulated by known gastric cancer genes in our GRNs, in which two genes are also cancer related (BPTF, CLCA1)." (PMID 29745833, 2018). "Interestingly, our data demonstrated that CREB1 was further elevated in secondary lymph node metastatic foci, suggesting an interesting link between CREB1 and lymph node metastasis of gastric cancer." (PMID 25825983, 2015). "In this study we found that miR-27b and miR-200b inhibited CREB1 expression in gastric cancer." (PMID 25825983, 2015). "To test whether miR-27b and miR-200b decreased CREB1 expression at mRNA level, we detected the CREB1 mRNA expression in gastric cancer cells transfected with miR-27b/miR-200b." (PMID 25825983, 2015).
gastric cancer (continued). "Reports on the relationship between CREB1 and gastric cancer metastasis remain scarce." (PMID 25825983, 2015). "We conclude that CREB1 is a promising biomarker to predict tumor metastasis and patient outcome in gastric cancer, and the miR-27b/miR-200b-CREB1 pathway may serve as a potential molecular target for the treatment of gastric cancer." (PMID 25825983, 2015). "Our findings suggest that CREB1, as a valuable biomarker of gastric cancer prognosis, may be a promising approach to gastric cancer treatment through the miR-27b/miR-200b-CREB1 pathway." (PMID 25825983, 2015). "In order to investigate whether miRNAs could regulate aberrant CREB1 expression in gastric cancer, we used prediction algorithms such as miRWalk and starBase to screen the miRNAs that potentially target CREB1." (PMID 25825983, 2015). "However, in the present study, we did not observe synergistic action of miR-27b and miR-200b in inhibiting CREB1 expression in gastric cancer." (PMID 25825983, 2015). "Subsequently, we tested whether miR-27b and miR-200b could synergistically inhibit CREB1 expression in gastric cancer." (PMID 25825983, 2015). "Moreover, our results showed that CREB1 is positively related with lymph node metastasis, distant metastasis and tumor stage in primary gastric cancer." (PMID 25825983, 2015). "Therefore, targeting the GATA6/miR-520b/CREB1 axis may be an effective approach for the treatment of gastric cancer." (PMID 33659248, 2021). "Therefore we could not conclude that miR-27b and miR-200b have synergistic roles in inhibiting CREB1 expression in gastric cancer." (PMID 25825983, 2015). "Importantly, CREB1 determination by IHC in the present experimental and evaluation system could distinguish lymph node metastasis in patients with gastric cancer and predict patients' prognosis." (PMID 25825983, 2015). "This suggested to us that aberrant overexpression of CREB1 in gastric cancer may be partially due to the downregulation of miR-27b/miR-200b in gastric cancer, and miR-27b/miR-200b could be potential CREB1 inhibitors to suppress carcinogenesis and tumor progression." (PMID 25825983, 2015). "However, the clinical significance and regulatory mechanisms of CREB1 expression in gastric cancer remain largely unknown." (PMID 25825983, 2015). "We suspect that this may be due to the fact that miR-27b has already strongly inhibited the expression of CREB1 by ~50% or more in gastric cancer cells; therefore, it's hard to see evidently stronger inhibitory effect of miR-27b/miR-200b co-transfection on CREB1 expression." (PMID 25825983, 2015). "In addition, univariate and multivariate Cox regressions further confirmed CREB1 as a risk factor (HR > 1) for patients with gastric cancer, though CREB1 seemed to bear no statistical significance in multivariate analysis." (PMID 25825983, 2015). "In gastric cancer, miR-182-5p has been reported to be sponged by circ-SFMBT2 to regulate the expression of CREB1 mRNA." (PMID 38877514, 2024). "The univariate analysis suggested that CREB1 expression, tumor size, depth of invasion, lymph node metastasis, distal metastasis and tumor stage were significantly correlated with OS and DFS of gastric cancer patients (P < 0.05)." (PMID 25825983, 2015). "Luciferase reporter experiment suggested that camp response element binding protein 1 (CREB1) had a negative correlation with miR-450a-5p expression, and knockdown of CREB1 alleviated gastric cancer growth." (PMID 33854971, 2021). "CREB1 expression was negative or weak in nontumorous gastric tissues, whereas weak to strong expression was observed in primary gastric cancer tissues." (PMID 25825983, 2015).
gastric cancer (continued). "In the current study, we found that CREB1 was overexpressed in gastric cancer tissues, in comparison with nontumorous gastric mucosa." (PMID 25825983, 2015).
Cerebral ischemia (56 papers, 2008 to 2025). Restriction of arterial blood supply to the brain associated with insufficient oxygenation to support the metabolic requirements of the tissue. "In cerebral ischemia, Creb1 is recognized as a key transcription factor in the cerebral ischemia response." (PMID 36301033, 2022). "There were 198 TFs identified after 6 h MCAO operation, and six TFs (Sox2, Smad3, FoxO1, Creb1, Egr,1 and Smad4) were considered as critical TFs in response to cerebral ischemia." (PMID 33414894, 2020).
diabetes (53 papers, 2010 to 2026). "Signaling from the proton-activated cell-surface receptor TDAG8 was rewired into a cAMP-sensitive response element operated by CREB1 for the expression of transgenes, including insulin for the treatment of diabetes-associated ketoacidosis." (PMID 36225597, 2022). "These include transcription factors concerned with the control of: adipogenesis (Pparγ, Klf15, Irf1, Creb1, Egr2, Gata3); lipogenesis (Mlxipl, Srebp1c); inflammation (Jun, Stat3); insulin signalling and diabetes susceptibility (Foxo1, Tcf7l2)." (PMID 21187013, 2010). "A comprehensive transcriptomic analysis involving type 2 diabetes mellitus patients further revealed that miR-124-3p and miR-16-5p affect the expression of genes such as CREB1, SP1, (both TFs in our analysis) SREBF1, and JUN (hub genes)." (PMID 36232337, 2022). "CREB1 is overactivated during diabetes, leading to fasting hyperglycaemia." (PMID 34164430, 2021).
neuroblastoma (53 papers, 2008 to 2025). Neuroblastoma (NB) is the most common solid, extracranial childhood tumor. "This CREB1 loss also resulted in poor relapse-free survival in children with neuroblastoma." (PMID 26148557, 2015). "It has recently been identified as a direct target of miR-205 in neuroblastoma and colon cancer, with miR-205 playing a role in inhibiting CREB1." (PMID 33918978, 2021). "CREB1 is involved in tumorigenic processes such as proliferation, invasion and metastasis and is overexpressed in many cancer types including neuroblastoma." (PMID 33918978, 2021). "Interestingly, upon examination of other known ODC1 transcriptional regulators, we found that CREB1 was expressed at higher levels in neuroblastoma compared to other adult tumor types, whereas WT1 was expressed at lower levels." (PMID 33918978, 2021). "Interestingly, CREB1 was consistently expressed at higher levels in neuroblastoma compared to the other tissues, and WT1 was expressed at lower levels in neuroblastoma compared to most of the adult cancer cohorts." (PMID 33918978, 2021). "CBP, CREB1 and p300 expression were individually prognostic for neuroblastoma patient outcome, with patients with low CBP, CREB1 or p300 mRNA expression only having an event-free survival rate of approximately 50%." (PMID 33968920, 2021).
Stroke (53 papers, 2012 to 2026). Sudden impairment of blood flow to a part of the brain due to occlusion or rupture of an artery to the brain. "The core targets of PPI are TNF,IL-6,ALB,AKT1,VEGFA, and CREB1, which play a key role in the regulation of stroke by DZSM." (PMID 34754318, 2021). "Furthermore, as one of cAMP-response-element binding protein (CREB) transcription factor, CREB1 is downregulated in the cancer stroke group compared with the stroke group alone, making plasticity and recovery of cortical circuits difficult." (PMID 38656987, 2024). "In our study, it is worth noting that the trends of CREB1 signaling activation persisted to be significantly increased in both CD11b+CD45int microglia and CD11b+CD45hi microglia/macrophage populations in the post-stroke cKO brains." (PMID 38509618, 2024). "Combined with our findings, RP11-111K18.2 may serve as a promising sponge for miR-128-3p and protect against stroke by elevating the CREB1 expression." (PMID 35096003, 2021). "One study has demonstrated that CREB1 is the target of miR-128 after stroke, and inhibition of miR-128 by ARPP21 leads to decreased neuronal apoptosis and promoted neurological function repair with the upregulation of CREB1 and BDNF." (PMID 35096003, 2021).
epilepsy (52 papers, 2012 to 2026). A brain disorder characterized by episodes of abnormally increased neuronal discharge resulting in transient episodes of sensory or motor neurological dysfunction, or psychic dysfunction. "In addition, there seems to be a strong convergence on the regulation of intracellular calcium levels as well as CREB1-related signaling, which have both been functionally linked to epilepsy before." (PMID 25676140, 2016). "It has been reported that CREB1 activation and downstream gene expression promote the development of epilepsy in several models." (PMID 37120983, 2023). "CREB1 is primarily known for its role in neurons; it is reported that CREB1 is active and plays a significant role in epilepsy." (PMID 37120983, 2023). "In the intra-amygdala kainate model of epilepsy in mice, the upregulation of miR-134 expression was followed by a corresponding decrease of transcript levels of Limk1 and Creb1 in the hippocampus." (PMID 36240080, 2022). "The increased mRNA expression of CREB-1 in the second hit PTZ group reflects the plausible role of CREB-1 in epilepsy as well as suggest that memory is impaired upon PTZ administration." (PMID 33732146, 2020). "CREB-1 exhibited a role in several biological process including the suppression of epilepsy as well as long-term potentiation of memory." (PMID 32260203, 2020). "The increased mRNA expression of CREB-1 in epileptic group compared to normal group reflects the plausible role of CREB-1 in epilepsy as well as suggests that memory is impaired in epileptic group." (PMID 32260203, 2020). "MiR-124 can attenuate epileptogenesis by inhibiting apoptosis, neuronal excitability, and prolonging onset latency via inhibiting expression of CREB1, C/EBPα, and Bcl2L13, while promoting epilepsy through microglia activation and inflammatory response." (PMID 31878035, 2019). "Nevertheless, a few functional themes such as vascular remodeling, neuropeptide signaling, lipid metabolism, epilepsy/immediate-early gene regulation, and calcium signaling were identified, with CREB1 as their central regulator (Online Resource 10, Supp." (PMID 29019056, 2018). "In patients with epilepsy, CREB1 is activated, and the related gene expression is upregulated." (PMID 37120983, 2023). "In all brain areas examined, MPTP treatment affected a set of mRNAs that is involved in epilepsy, which is reflected by the presence of the epilepsy-regulating transcription factor CREB1, the convulsants bicuculline and dalfampridine, and the biofunction “epilepsy”." (PMID 29019056, 2018). "Few studies have investigated the role of genes such as neuropeptide Y (NPY) gene, CREB1, and brain-derived neurotrophic factor (BDNF) that interact with each other to control epilepsy and enhance long term memory." (PMID 31708779, 2019).